ACHE (acetylcholinesterase (Yt blood group))
Diseases named in the same sentence as ACHE in open-access papers (continued):
Sharing a sentence is not in itself a finding about the gene and the disease.
Alzheimer disease (continued). "Then, we integrated eight of icariin’s putative targets which were involved in above pathways, together with two known icariin’s targets (AChE and PDE5), and “Alzheimer’s Disease Pathway” (defined in KEGG (has:05010)) into a network." (PMID 26784184, 2016). "Inhibition of AChE and BChE are the key enzymes in the breakdown of acetylcholine and butyrylcholine that may be considered as one of the treatment approaches against several neurological disorders such as Alzheimer’s disease, senile dementia, ataxia, and myasthenia gravis." (PMID 25889712, 2015). "The ACHE, CHAT, and SLC18A13 genes have been investigated as functional candidates for Alzheimer’s disease." (PMID 25384021, 2014). "(-)-Phenserine is a reversible AChE inhibitor possessing neuroprotective and amyloid precursor protein lowering actions that reached Phase III clinical trials for Alzheimer's Disease where it exhibited a wide safety margin." (PMID 24955574, 2014). "C1a reversibly inhibits AChE and BChE without undesirable peripheral effects, making it a promising candidate for the treatment of Alzheimer’s disease." (PMID 39201735, 2024). "Current research indicates that increasing brain cholinergic neurotransmission by decreasing the chemical reaction to AChE hydrolysis is the most effective therapy for Alzheimer’s disease, although the pathophysiology of the illness is not entirely understood." (PMID 38542869, 2024). "This study shows that CID: 12000657 could be used as an AChE inhibitor and CID: 135398658 as a BuChE inhibitor to treat Alzheimer’s disease and other neurological disorders." (PMID 37049419, 2023). "Likewise, DL strongly inhibited cholinergic (AChE and BChE) and β-amyloid formation enzymes (BACE-1), thereby showing potential as an effective agent to control Alzheimer’s disease." (PMID 38066118, 2023). "In addition, results from molecular docking studies were crucial for validating the interactions of twenty phytocompounds with high binding affinity for the target receptors AChE, COX2 and MMP8, which are involved in the physiopathology of Alzheimer’s disease." (PMID 37762197, 2023). "Furthermore, the alkaloid extracts of the three species will be evaluated in terms of bioactivity and inhibition of AChE and BuChE enzymes in order to identify possible species that could represent new sources of cholinesterase inhibitors for the palliative treatment of Alzheimer’s disease." (PMID 37513280, 2023). "In Alzheimer’s disease (AD), the reduction in acetylcholinesterase (AChE) enzymatic activity is not paralleled with changes in its protein levels, suggesting the presence of a considerable enzymatically inactive pool in the brain." (PMID 36674948, 2023). "For instance, several natural-based enzyme inhibitors, such as orlistat (pancreatic lipase inhibitor), acarbose (α-glucosidase), and galantamine (AChE inhibitor), have already been used to treat some major diseases, such as type-2-diabetes mellitus (T2DM), Alzheimer’s disease (AD), and obesity." (PMID 37836131, 2023). "AChE, NMDAR, β-secretase, Aβ oligomers, Aβ plaques, GSK-3β, neurofibrillary tangles, Ca2+ ions, and reactive oxygen species are elements involved in the pathogenesis of Alzheimer’s disease (AD) and represent significant potential targets for treatment." (PMID 38125832, 2023). "The NLRP3, BACE1, AChE, and GSK-3β are closely related to Alzheimer’s disease." (PMID 35991454, 2022). "Using pharmacology networking to specify the targets of the identified compounds with a relationship to Alzheimer’s disease, it was possible to identify the VEGFA, AChE, and DRD2 genes as the top correlated genes to Alzheimer’s disease with 8, 8, and 6 interactions in the same order." (PMID 36557216, 2022). "Inhibitory activities against the key enzymes relevant to obesity (lipase), diabetes (α-glucosidase and α-amylase), and Alzheimer’s disease (AChE, BChE, and BACE-1) and the nonenzymatic glycation reaction were also assessed." (PMID 35161275, 2022).
Alzheimer disease (continued). "Moreover, ginsenosides (Rb1, Rb2, Rc, Re, Rg1, and Rg3) act through inhibition of AChE, BChE, and BACE1 activities, as well as scavenging of ONOO(-) and inhibition of nitrotyrosine formation, to treat or prevent Alzheimer's disease." (PMID 35746960, 2022). "It was reported that the treatment of early and moderate Alzheimer’s disease has largely involved the replacement of neurotransmitters that are known to be lacking, mostly based on AChE inhibition." (PMID 35336618, 2022). "It is believed that α-glucosidase, acetylcholinesterase (AChE), and tyrosinase are important metabolic enzymes relating with oxidative stress, and they are shown to be the key targets of T2DM, Alzheimer’s disease (AD), mammalian melanogenesis, and fruit or vegetable enzymatic browning, respectively." (PMID 33546380, 2021). "In fact, it has been reported that AchE activity is reduced by 67% compared to the normal level in the hippocampus and temporal lobe during the progression of Alzheimer’s disease while the BchE activity is gone up to 165%, relative to normal levels." (PMID 34679706, 2021). "Biological activities of further IAs, isolated and tested in connection with potential treatment of Alzheimer’s disease, from 2010 (alkaloids only included with an IC50 value ≤ 30 μM for AChE or BuChE; an IC50 ≤ 200 μM for POP; all results for MAO-A and inhibition of Aβ-aggregation are included)." (PMID 34500673, 2021). "Acetylcholinesterase (AChE) and beta-secretase (BACE-1) are two attractive targets in the discovery of novel substances that could control multiple aspects of Alzheimer’s disease (AD)." (PMID 32867308, 2020). "For example, 1 is reported to exhibit inhibitory activity towards both acetylcholinesterase (AChE) and β-secretase (BACE-1), which suggests that 1 could hold promise as a dual mechanism-of-action treatment for Alzheimer’s disease." (PMID 33178356, 2020). "Thus, the therapeutics access is mainly focused on the inhibition of AChE and N-methyl-D-aspartate (NMDA) receptors for treating Alzheimer's disease currently." (PMID 29507588, 2018). "In another paper, gomisin D showed potent inhibition of the AChE activity with the IC50 value as 7.84 ± 0.62 μM, implying that it may be the active component in the plants that is useful in treatment of Alzheimer’s disease." (PMID 30524412, 2018). "The acetylcholinesterase (AChE) and butyrylcholinesterase (BChE) inhibitory effects of ME and HWE were moderate and comparable with galanthamine, the standard drug to treat early stages of Alzheimer’s disease (AD)." (PMID 27196881, 2016). "When the AChE inhibitor tacrine, a drug used in the past to treat Alzheimer's disease, was perfused on living cells expressing CLASH-AChE/HCA, tacrine displaced the secondary ligand from AChE, allowing the benzenesulfonamide to bind HCA and leading to high FRET efficiency of the sensor." (PMID 26198003, 2015). "Additionally, we conducted ADME (Absorption, Distribution, Metabolism, and Excretion) and toxicity (T) analyses of the selected top dual inhibitors to find dual inhibitors of AChE and BACE1 for developing lead compounds with fewer side effects and more potency against Alzheimer’s disease." (PMID 40560959, 2025). "Among them, harmine has been reported to inhibit MAO, AChE, and dual-specificity tyrosine-phosphorylation-regulated kinase 1A (DYRK1A), thereby exerting various pharmacological effects, including antitumor, antioxidant, anti-inflammatory, anti-Alzheimer’s disease and antidepressant effects." (PMID 40693273, 2025). "Additionally, its potential utilization in treating Alzheimer’s disease, a neuroinflammatory disease, was demonstrated with a half-maximal inhibitory concentration (IC50) of 4.51 ± 0.03 μM on acetylcholinesterase (AChE), which is a cholinergic enzyme in the nervous system." (PMID 39409020, 2024).
Alzheimer disease (continued). "These compounds present a novel scaffold for drug development, as current therapies for Alzheimer’s disease (AD) primarily use selective AChE inhibitors, while non-selective inhibitors of cholinesterases (ChEs) are preferred in Parkinson’s and all stages of AD." (PMID 39595567, 2024). "As Alzheimer’s disease (AD) is among the most severe threats to human health and alkaloids usually cover related bioactivities, the fermentation extracts of strain ACD-5 were screened for related antioxidant, AChE inhibitory, anti-neuroinflammatory, and anti-Aβ aggregation activities." (PMID 37206330, 2023). "We reported the VEGFA, AChE, and DRD2 genes as the top correlated genes to memory disorders and Alzheimer’s disease in our gene set using a theoretical computerized chemical–biological relationship between identified metabolites from OEP extract and Alzheimer’s disease." (PMID 36557216, 2022). "TSAIII up-regulated the acetylcholine contents, inhibited the AChE activity and decreased the expression of TNF-α and IL-1β in scopolamine-treated mice brain models, meaning that TSAIII may be across the blood–brain barrier (BBB) in Alzheimer’s disease." (PMID 36611961, 2022). "Furthermore, these ceanothanes not only bind to the AChE catalytic site but also to the PAS and in this way could inhibit the formation of senile plaques typical of Alzheimer’s disease." (PMID 35888792, 2022). "However, unfortunately, the clinical studies undertaken have demonstrated that the therapeutic potential of AChE inhibitors in the management of Alzheimer’s disease did not perform as expected." (PMID 35956919, 2022). "These include combinations of carbamates (reversible AChE inhibitors) and central anticholinergics or NMDA receptor antagonists, benzodiazepines or partial agonists for benzodiazepine receptor, and other central AChE inhibitors approved for Alzheimer’s disease." (PMID 34070145, 2021). "In March 2011 NICE introduced guidelines that recommended the prescription of memantine for patients with moderate to severe Alzheimer’s disease or for those people who could not tolerate AChE inhibitors." (PMID 29843807, 2018). "Interestingly, 5b, not only natural product but also one of the favored starting materials for rutaecarpine synthesis, showed promising inhibitory activity on AChE (IC50 = 83.38 μM), implying a new vista towards designing new analogues of rutaecarpine for the treatment of Alzheimer’s disease." (PMID 26111170, 2015). "Likewise, for the enzyme inhibition tests, the IC50 values for cholinesterase inhibition (AChE and BCHE) were close to those of the reference compound, galantamine, which served as the positive control since it is clinically applied in the management of mild Alzheimer’s disease." (PMID 41451025, 2025). "Therefore, Sarcorucinine-D could be considered a potential lead molecule for Alzheimer’s disease based on its properties as a noncompetitive AChE inhibitor and a Ca2+ channel blocker." (PMID 35684298, 2022). "This led to a further revision being made to the NICE guidance at the end of March 2011, which recommended AChE inhibitors for patients with mild to moderate Alzheimer’s disease and memantine for patients with moderate to severe Alzheimer’s disease or who could not tolerate AChE inhibitors." (PMID 29843807, 2018). "Nowadays, according to its neuroprotective properties and with the “glutamate hypothesis” of Alzheimer's disease, memantine is recommended for treatment of moderate Alzheimer's disease in people who do not tolerate AChE inhibitors and for management of severe Alzheimer's disease." (PMID 28243470, 2017). "In a meta-analysis, there was small advantage of AChE inhibitors over placebo with a modest improvement of 1.72 points on the Neuropsychiatric Inventory (NPI) and 0.03 points on the Alzheimer Disease Assessment Scale, noncognitive (ADAS-noncog)." (PMID 23450042, 2012).
Cognitive impairment (252 papers, 2006 to 2026). Abnormal cognition is characterized by deficits in thinking, reasoning, or remembering. "It significantly enhances the AChE activity, leading to accelerated breakdown of ACh in the brain, which is associated with cognitive deficits, and impaired learning and short-term memory." (PMID 40565209, 2025). "Under normal conditions, AChE activity is essential for regulating neurotransmission; however, its dysregulation is strongly linked to cognitive deficits." (PMID 40726602, 2025). "Dysregulation of AChE activity is often linked to cognitive impairments and neurodegenerative disorders, including MS, where demyelination and inflammation disrupt cholinergic signaling." (PMID 41155593, 2025). "Results from 22 clinical trials have demonstrated the efficacy of AChE inhibitors in treating cognitive impairments associated with AD." (PMID 39796512, 2024). "The overstimulation of acetylcholinesterase (AChE) can cause a decline in ACh levels, leading to the frequent prescription of AChE inhibitors (AChEIs), such as tacrine (TA), as useful drugs to treat cognitive impairments in dementia patients." (PMID 39338335, 2024). "Acetylcholinesterase (AchE) is the main pharmacological target of most anti-Alzheimer drugs, since cholinergic neuron loss has been closely related to memory loss and cognitive impairment." (PMID 39202843, 2024). "Increased AChE activity accelerates acetylcholine metabolism in the synaptic cleft and reduces cholinergic neurotransmission efficiency, causing progressive cognitive impairments." (PMID 40066120, 2024). "Diabetes-related cognitive deficits, memory loss, and neurophysiological abnormalities were found to include AChE." (PMID 38982468, 2024). "In an in vivo mouse model, Mep-S attenuated scopolamine-caused cognitive deficits with inhibition of apoptotic neuronal death and brain AChE activity." (PMID 36819782, 2023). "Remarkably, increased activity of AChE, an enzyme that hydrolyses ACh, has been linked to the pathomechanism of cognitive impairments and memory loss in various neurocognitive diseases, including AD." (PMID 37509038, 2023). "AChE is involved in the metabolism of brain acetylcholine and is implicated in several cognitive disorders, including AD, schizophrenia, anxiety, narcolepsy, and epilepsy." (PMID 37695764, 2023). "Reduced AChE activity together with mitochondrial dysfunction, and inflammation are the prime causes of impaired memory and cognitive impairment." (PMID 36449200, 2023). "In the current study, STZ mastered the occurrence of AD through three major mechanisms, beginning with its effect on AChE which led to cholinergic deficiency and cognitive impairment." (PMID 37598127, 2023). "For a period of time, the inhibition of AChE activity was thought to be the main mechanism by which OPs caused neurotoxicity, including cognitive impairment." (PMID 37106826, 2023). "Next, we measured the levels of AChE in each group, because cholinergic dysfunction is known to be involved in cognitive impairment caused by CCH." (PMID 37513692, 2023). "In our study, we found that T2DM rats showed a significant rise in AChE activity, indicating cholinergic dysfunctioning that would have caused cognitive impairment in diabetic rats." (PMID 36362316, 2022). "The outcomes of this study support the use of LFD for cognitive disorders and highlight its underlying mechanism, targeting AChE, DNA-POL, NF-KB, and TNF-α, etc., for the first time." (PMID 36080247, 2022). "The reduced expression of ACHE has been linked to depression and cognitive deficits in human studies." (PMID 34358063, 2021). "The ability of E100 to enhance cholinergic activity in VPA mice and to exert its potential effect on cognitive deficit associated with sociability impairments was confirmed by measuring AChE activity in the cerebellum." (PMID 32503208, 2020). "AChE inhibitors are used clinically to treat neurological diseases associated with cognitive impairments." (PMID 30483056, 2018).
Cognitive impairment (continued). "Several lines of evidence have indicated that significantly lower cortical and thalamic AChE activity are associated with declines in cognitive impairment." (PMID 29392081, 2018). "In line to this notion, the loss of AChE activity was observed in mild cognitive impairment and in early AD." (PMID 29535608, 2018). "AChE has been identified as a promising target for treatment of cognitive impairments associated with Alzheimer’s by applying its enzyme inhibitors." (PMID 30217053, 2018). "Our report on cognitive impairment and global loss of AChE activity in brain of hypercholesterolemic mice have resemblance with the with symptoms and pathology of AD7–12,51,52." (PMID 29263397, 2017). "The Aβ1–42-induced reduction of acetylcholine ACh and elevation of AChE is also associated with cognitive impairment." (PMID 29137190, 2017). "High-fat diet-associated diabetes caused cognitive impairment, which were accompanied by increased AChE activity and MDA levels in mice brains." (PMID 26161118, 2015). "Acetylcholinesterase (AChE) modulates acetylcholine to proper levels by degradation, thus, excessive AChE activity leads to constant acetylcholine deficiency, causing memory and cognitive impairment in AD." (PMID 25372040, 2014). "In AD, ACh depletion is associated with cognitive deficits, arousing the cholinergic hypothesis in the physiopathology of AD and thus the search for inhibitors of its degrading enzymes, acetylcholinesterase (AChE) and butyrylcholinesterase (BuChE)." (PMID 39944895, 2025). "In AD, cognitive impairment is linked to brain levels of ACh and AChE." (PMID 40699625, 2025). "Therefore, the ability of these plant-derived compounds to inhibit both AChE and BChE indicates a promising therapeutic strategy for restoring cholinergic function and alleviating cognitive impairments associated with AD." (PMID 40002547, 2025). "Despite pyocyanin’s effective inhibitory activity against AChE and 5-lipoxygenase, its use as a neuroprotectant is limited by its ability to penetrate the blood–brain barrier which could potentially cause cognitive impairment due to reduced brain function." (PMID 38341389, 2024). "As cognitive deficits are a risk factor for the development of psychosis in PD, it is conceivable that treatment with AchE inhibitors could lead to a reduction of psychotic experiences." (PMID 39046524, 2024). "In T2DM, chronic hyperglycemia and insulin resistance may increase AChE levels, which impairs ACh signaling, exacerbates insulin resistance in the brain, and heightens cognitive deficit risk." (PMID 39766390, 2024). "Cholinergic neurotransmission is essential for maintaining learning and memory processes, and the enzyme acetylcholinesterase (AChE) is altered in the brains of AD patients, reducing the pool of available Ach, which is associated with severe cognitive deficits." (PMID 37509151, 2023). "Flavonoids exhibit AChE inhibitory effects due to their antioxidant potential, which is linked to enhancing the antioxidant defence mechanism of cholinergic neurons and thus alleviating behavioural and cognitive deficits." (PMID 36760351, 2023). "In this study, the isolated aged untreated mice brains have shown elevated AChE activity that contributes to diminished cholinergic neurotransmission and associated cognitive impairment in these animals, as appropriate cholinergic neurotransmission is fundamental for the formation of memory." (PMID 36771374, 2023). "Cognitive impairment could be derived from acetylcholine (Ach) deficiency caused by excessive AChE activity, and studies suggests that inactivation of AChE activity improves memory impairment." (PMID 38034861, 2023). "In the present study, Scop-treated rats showed an increase in hippocampal AChE activity, leading to cognitive impairment and memory loss, as in tune with previously documented data, causing amplified acetylcholine degradation and impairment in learning and memory." (PMID 36296710, 2022).